INS (insulin)
Diseases named in the same sentence as INS in open-access papers (continued):
Sharing a sentence is not in itself a finding about the gene and the disease.
diabetes (continued). "This study evaluated thyroid cancer risk with regards to diabetes status and diabetes duration, and with the use of anti-diabetic drugs including sulfonylurea, metformin, insulin, acarbose, pioglitazone and rosiglitazone, by using a population-based reimbursement database in Taiwan." (PMID 23300866, 2012). "However, in another study, silymarin was associated with decrease in resistance to insulin and serum insulin level in patients with cirrhosis and diabetes." (PMID 23087748, 2012). "Increased risk of breast cancer has been associated with diabetes in numerous epidemiological studies, therefore we also studied the effect of insulin analogues on the production of PIP3 in breast cancer derived cell lines using a new, highly sensitive BRET-based assay." (PMID 22848683, 2012). "Moreover, new onset T1D occurring in NOD mice is associated with a type 2 diabetes mellitus (T2D) like state, characterized by defective insulin signaling and thus insulin resistance." (PMID 22606220, 2012). "Whole-pancreas transplantation can restore endogenous insulin production, but it has rarely been carried out in children with diabetes due to the risk of perioperative morbidity related to the damage by digestive enzymes from the exocrine pancreas during the surgical procedure." (PMID 22611393, 2012). "Additionally, low 25OHD concentration was significantly related to diabetes risk and the effect of 25OHD on glucose metabolism was more closely associated with decreased insulin sensitivity in the Korean population." (PMID 22247968, 2012). "Another cross-sectional study involving 52 consecutive patients recruited from a diabetes-obesity clinic found that after adjusting for age, gender, BMI, duration of diabetes, and insulin dose, increased severity of OSA was associated with increased A1c levels." (PMID 23015803, 2012). "Similarly, in the present study, insulin resistance with high fasting insulin levels had a positive association with the number of MetS components and incidence of diabetes." (PMID 22537054, 2012). "This is interesting in light of the fact that patients with diabetes mellitus may have an increased risk of developing PD and more than 60% of the PD patients have impaired insulin signaling and are glucose intolerant." (PMID 22952715, 2012). "After exclusion of insulin users, HRs for the association between carbohydrate intake and all-cause mortality risk were 2.20 [CI, 1.36–3.55] and 0.89 [CI, 0.74–1.08] in normal and overweight diabetes patients respectively." (PMID 22927948, 2012). "Since the association with diabetes could be explained by effects on insulin secretion, we investigated whether patients with diabetes risk alleles at rs7903146 might have an altered hypoglycaemic response to sulfonylureas (SUs)." (PMID 21349175, 2011). "Caused by complex interactions of multiple factors, diabetes mellitus type 2 (type 2 diabetes) is characterized by decreased secretion of insulin by the pancreas and resistance to the action of insulin in various tissues (eg muscle, liver, adipose), leading to impaired glucose uptake." (PMID 21375727, 2011). "Alloxan causes diabetes through its ability to generate reactive oxygen species (ROS), which leads to a massive increase in cytosolic calcium concentration and, consequently, a rapid destruction in the insulin-producing beta cells of the pancreas." (PMID 20953386, 2011). "Although worm uses insulin to control both its fat metabolism and its hibernation program, the worm does not live long enough to develop diabetes, but seems to have the same genetic pathways associated with human diabetes." (PMID 22582147, 2011). "The possible pathogenic relevance of our findings is supported by recent studies showing that abnormal insulin secretion and response and abnormal glucose tolerance and risk of diabetes are found already in drug-naïve first-episode patients with schizophrenia." (PMID 21429189, 2011).
diabetes (continued). "Excessive glucose in the blood and the loss of insulin produces vascular damage via glycosylation and activation of oxidative and nitrosative stress linked to all of the symptoms associated with diabetes, including peripheral and autonomic neuropathy, nephropathy, and retinopathy." (PMID 23724283, 2011). "Impaired insulin signaling increases risk of Alzheimer disease, cognitive disabilities in diabetes mellitus and decreases cerebrocortical beta activity in overweight humans whereas intranasal administration of insulin improves hippocampal-dependent memory function." (PMID 21264261, 2011). "In this respect, previous studies showed heart failure to be an insulin-resistant state that may predispose to diabetes." (PMID 21569580, 2011). "Interestingly, position B24 and B25 are also sites of diabetes-associated mutations (B24Ser – insulin Los Angeles; B25Leu – insulin Chicago), which underline the importance of the aromatic region in receptor binding." (PMID 21625452, 2011). "That diabetes is the most common disease – at least in younger age groups – might be associated with the protein nature of insulin, whereas the other glands produce smaller molecules that may be less antigenic." (PMID 21143521, 2011). "However, the current standard of care, which consists of constant monitoring and precise insulin loading through injections, puts patients at risk for acute diabetes complications." (PMID 22047106, 2011). "This study suggests BBG may slow the deterioration of insulin sensitivity for individuals at increased risk for diabetes mellitus." (PMID 21846371, 2011). "To date, no large-scale epidemiological studies have been conducted to explore the relationship between low serum amylase levels and cardiometabolic diseases associated with insulin resistance and/or inadequate insulin secretion, such as metabolic syndrome (MetS) and diabetes." (PMID 21496338, 2011). "There is some evidence that the role of reduced insulin secretion and reduced insulin sensitivity in determining diabetes risk may differ among populations." (PMID 21731609, 2011). "This may reflect treatment earlier in the disease and supports the inclusion of insulin as a second step in the American Diabetes Association/European Association for the Study of Diabetes treatment algorithm." (PMID 21481127, 2011). "Hence, smokers who carry S319 allele, and therefore are exposed to compromised insulin function, are at increased risk of developing diabetes." (PMID 21208426, 2011). "Diabetes is caused by a defect in insulin production, insulin action, or both." (PMID 20924500, 2011). "Our findings differ from genome wide association studies of fasting insulin and other diabetes related traits in European populations, highlighting the continued need to investigate unique genetic influences for understudied populations such as African Americans." (PMID 21901158, 2011). "HF can be regarded as an insulin resistant state with increased risk of diabetes." (PMID 21999413, 2011). "In prostate cancer patients who undergo chemical castration therapy, testosterone levels are suddenly and drastically reduced, resulting in increased fat deposition, increased insulin levels, impaired insulin sensitivity, and increased risk of diabetes and MetS classification." (PMID 22044661, 2011). "However, by one month after birth, transgenic mice expressing any of the three Ran variants exhibited overt diabetes, with hyperglycemia, reduced insulin production, and nearly complete loss of islet number and islet mass, in vivo." (PMID 22114719, 2011). "Indeed other studies suggest that high fiber diets improve insulin sensitivity and other cardiovascular risk factors in individuals with hyperinsulinaemia and diabetes in comparison with diets high in refined carbohydrates." (PMID 21524314, 2011). "In addition to insulin sensitivity, insulin insufficiency is another important causative factor of diabetes." (PMID 22363882, 2011).
diabetes (continued). "Diabetes mellitus (DM) is a metabolic disorder characterized by hyperglycemia and alterations in carbohydrate, fat, and protein metabolism, associated with absolute or relative deficiencies in insulin secretion and/or insulin action." (PMID 22016649, 2011). "Loss of beta-cells in both types of diabetes implies that restoration of endogenous insulin secretion and normalisation of hyperglycemia in such patients might be accomplished through the supplementation of islet cells." (PMID 21716694, 2011). "In addition this genotype has been associated to higher exercise energy efficiency, higher risk in obesity, higher incidence of diabetes, and a higher acute insulin response to glucose." (PMID 22216339, 2011). "In particular, weight loss in type 2 diabetes is associated with improved insulin action and enhanced glycemic control, and it may favorably affect other comorbidites associated with diabetes such as hypertension and dyslipidemia." (PMID 21529363, 2011). "In summary, we have defined the molecular pathogenesis of MIDY as a syndrome in which mutant proinsulins use unpaired cysteine residues to recruit nonmutant proinsulins into disulfide-linked complexes, blocking insulin production that leads to insulin-deficiency, beta cell ER stress, and diabetes." (PMID 20948967, 2010). "Surprisingly, these animals are protected from the development of obesity-associated deterioration of glucose metabolism, thereby defining insulin action in inflammatory cells as a novel and promising target for therapeutic intervention against obesity-associated diabetes mellitus." (PMID 20463885, 2010). "Additionally, we found that younger age, having less than a middle school education, injecting insulin, and being a current smoking were all independently associated with physical inactivity in diabetics." (PMID 20500890, 2010). "On the other hand, a decrease of leptin levels associated with the reduction of body mass has been implicated in the pathogenesis of insulin-deficient diabetes, in which leptin replacement improved insulin sensitivity and decreased hepatic triglyceride content." (PMID 20953376, 2010). "Because hyperglycemia is known to be responsible for the functional abnormalities associated with diabetes, any beneficial effects of genistein might be secondary to its action on insulin secretion or hyperglycemia." (PMID 21042558, 2010). "Thus, a nuclear import inhibitor extinguished autoimmune inflammation-driven islet loss and prevented further progression of diabetes thereby obviating the need for insulin replacement therapy." (PMID 20949090, 2010). "The sum of these findings indicates that genetic defects in the PERK/eIF2α signal transduction pathway are sufficient to disrupt regulated mRNA translation and interfere with ER function in the β-cell, thereby causing reduced insulin secretion, β-cell death and diabetes in mice and humans." (PMID 21029306, 2010). "Thus, the altered expression of CDKAL1 is probably associated with reduced glucose-induced first-phase insulin exocytosis and thus confers an increased risk for diabetes." (PMID 21151568, 2010). "Insulin sensitizers have shown some benefit in the risk of stroke in patients with diabetes." (PMID 20701768, 2010). "Differentiating preadipocytes with low C/EBPα and PPARγ can still accumulate lipid when exposed to fatty acids but are insulin resistant and dysfunctional, consistent with accretion of the large, insulin-resistant, C/EBPα- and PPARγ-deficient fat cells in obesity that are associated with diabetes." (PMID 20701600, 2010). "However, the findings of early age for the onset of diabetes and its complication in Bangladesh, and correlation insulin treatment with increased risk for DPN deserve further attention." (PMID 20431800, 2010). "Resistance of muscle to the effects of insulin is a hallmark of pre-diabetes." (PMID 20532430, 2010).
diabetes (continued). "In addition, they examined 223 patients from the population-based Norwegian Childhood Diabetes Registry and found an R55C INS mutation." (PMID 20226046, 2010). "(b) The other form, diabetes type 1B (diabetes with idiopathic loss of β-cell function) is comparatively less common, lacks the autoimmunity connection and might need insulin replacement therapy in affected patients." (PMID 20350307, 2010). "Loss of regular oscillations of insulin is an early indicator of diabetes." (PMID 19961265, 2009). "The molecular mechanisms behind the effect of ADAMTS9 on peripheral insulin action and risk of diabetes are unknown." (PMID 19789630, 2009). "Thus, inhibition of calcineurin leads to decreased insulin transcription and, then, to post-transplantation Diabetes mellitus – PTDM, the most known adverse effect caused by immunosuppressive treatment with tacrolimus." (PMID 19243597, 2009). "Clearly, β cell dysfunction is a hallmark of both types of diabetes and a genetic variant that predisposes an individual toward reduced insulin secretion potentially could increase the risk of developing diabetes." (PMID 19691832, 2009). "However, given the great benefits of weight loss on improved glucose tolerance and insulin sensitivity in people with pre- or newly diagnosed diabetes, it is important to educate and encourage these patients to lose excess weight." (PMID 19267925, 2009). "Diabetes can be caused by too little insulin (type I), resistance to insulin (type II), or by both." (PMID 19761624, 2009). "Furthermore, SGK1 activity has been linked to diabetes through glucocorticoid-mediated inhibition of insulin secretion." (PMID 19461886, 2009). "As recent GWA studies mainly detected genes involved in insulin secretion as diabetes risk genes, one may assume that NR4A3 genetic variants have an impact on diabetes prevalence." (PMID 19682370, 2009). "For example, the Canadian Diabetes Association recommended in 2003 that insulin glargine could be used as an alternative to generic long-acting insulin for the treatment of diabetes." (PMID 19497114, 2009). "Previous research has suggested that insulin therapy may be associated with an increased risk of heart failure and also an increased risk of mortality in people with diabetes and heart failure." (PMID 19203392, 2009). "Alloxan, a beta cytotoxin induces diabetes by free radical generation, which causes a massive reduction of the insulin secreting β-cells of the islets of langerhans, resulting in a decrease in endogenous insulin release, which paves the ways for the decreased utilization of glucose by the tissue." (PMID 19943967, 2009). "However there are likely to be direct medical cost savings associated with immediate initiation of insulin due to diabetes-related complications avoided." (PMID 19804622, 2009). "We discovered that the diabetes in Perk KO mice was due to hypoinsulinemia associated with low insulin-secreting beta-cell mass caused by diminished beta-cell proliferation and impaired insulin secretion." (PMID 19956728, 2009). "Analyzing four selected tagging SNPs of SGK, the SNP rs9402571 was consistently found to be associated with altered insulin secretion in both prediabetic populations, and was further confirmed to associate with the prevalence of type 2 diabetes mellitus in the population-based cohort." (PMID 18985156, 2008). "Absence or insufficient production of insulin causes diabetes." (PMID 21394262, 2008). "Among the arsenic-interacting genes in CTD, 105 are associated with diabetes directly or are annotated with a GO term or KEGG pathway involved in insulin or glucose signaling or metabolism, providing a basis for examining the etiology of arsenic-associated diabetes." (PMID 18845002, 2008). "Loss of insulin pulsatility is observed in patients of both type 1 diabetes (T1D) and type 2 diabetes (T2D), and in relatives with mild glucose intolerance or in individuals at risk for diabetes." (PMID 18673579, 2008).
diabetes (continued). "Diabetes mellitus is caused by the reduced secretion and/or diminished action of insulin." (PMID 18828926, 2008). "Although the VA/Department of Defense (DoD) diabetes guidelines already included a risk-stratified approach for diabetes eye care based on insulin use, level of glycemic control, and risk status, the approach was difficult to implement as a performance measure." (PMID 18353187, 2008). "We hypothesized that common polymorphisms in the ARNT gene would alter its function or expression, and in turn increase the susceptibility to diabetes by affecting glucose-stimulated insulin secretion." (PMID 18366646, 2008). "The Canadian clinical practice guideline issued by the Canadian Diabetes Association in the year 2003 with a recommendation to test three or more times a day in patients receiving insulin and at least once a day in patients receiving oral antihyperglycemic agents." (PMID 18501012, 2008). "Fat is now known to secrete humoral factors and some of these (e.g. leptin, adiponectin and resistin) can modulate insulin sensitivity; thus, the altered production of these adipokines in obesity could be involved in predisposition to diabetes." (PMID 19007436, 2008). "Defects in insulin production and secretion, as observed in type 1 diabetes due to autoimmune destruction of the pancreatic beta cells, result in chronic hyperglycemia, which is responsible for most of the secondary complications associated with diabetes." (PMID 17941991, 2007). "It is therefore difficult to determine from current research whether the association between diabetes and cardiovascular disease is primarily driven by insulin resistance–related factors, insulin secretion–related factors, or both." (PMID 17760500, 2007). "Studies suggest that coffee drinking is associated with a higher insulin sensitivity and a lower risk of type 2 diabetes, and that total caffeine intake from all sources was associated with a significantly lower risk for diabetes in men and women." (PMID 17919327, 2007). "The importance of insulin pulsatility in glucose regulation is further indicated by the loss of it observed in patients of both type 1 diabetes (T1D) and type 2 diabetes (T2D), which together constitute more than 95% of all diabetes cases." (PMID 17912360, 2007). "A variety of mechanisms has been postulated in the risk of Alzheimer's disease and type 2 diabetes mellitus: metabolic abnormalities of insulin resistance (dyslipidemia, hypertension), hyperglycemia per se or insulin, by disturbing synaptic plasticity, learning and memory." (PMID 17096857, 2006). "In addition, in the present study, treatment with insulin prevented the occurrence of alterations caused by diabetes, i.e. bradycardia, hypotension and low +dP/dtmax and low -dP/dtmax." (PMID 17144912, 2006). "In summary, out of the top 10 genes identified by FM-test, we could find 6 of them in the literature about their association with insulin metabolism and diabetes." (PMID 17217525, 2006). "Because these genes are associated with sugar metabolism, insulin function, and diabetes in mammals, our data indicate that MeHg may disrupt these functions particularly in males, and there may be a link between MeHg exposure and certain metabolic diseases." (PMID 16966085, 2006). "Our finding of higher rates of microvascular complications in T allele patients with diabetes is consistent with specific dysfunction of insulin production in the beta cell present with the TCF7L2 polymorphism, perhaps leading to greater exposure to hyperglycemia-mediated damage." (PMID 17181866, 2006). "Concentric remodeling may be related to specific pathophysiological adaptations, particularly related to glucose and insulin metabolism and studies in contemporary cohorts have also shown an association of concentric forms with diabetes." (PMID 15963236, 2005).